ACTN1 (actinin alpha 1)
Diseases named in the same sentence as ACTN1 in open-access papers (continued):
Sharing a sentence is not in itself a finding about the gene and the disease.
glioma (4 papers, 2020 to 2024). A benign or malignant brain and spinal cord tumor that arises from glial cells (astrocytes, oligodendrocytes, ependymal cells). "A four-gene signature (ACTN1, AQP1, LAMC3, NRM) prognostic risk model was constructed among the differentially expressed genes (DEGs) identified in the grade II/III gliomas molecular subtypes." (PMID 38307919, 2024). "Based on this, we further validated the clinical relevance of ACTN1 protein expression using immunohistochemistry and found that ACTN1 expression is negatively correlated with grade II/III gliomas patient prognosis." (PMID 38307919, 2024). "Immunohistochemistry analysis further demonstrated that ACTN1 protein expression in grade II/III gliomas was negatively correlated with patient overall survival." (PMID 38307919, 2024). "In the context of the four-gene signature's relationship with immunity and its correlation with grade II/III gliomas patient prognosis, we explored the potential link between ACTN1 and T cell exhaustion within tumors." (PMID 38307919, 2024). "Actinin alpha 1 (ACTN1) has been identified as a glioma microenvironment-related gene with prognostic value in malignant gliomas." (PMID 34805164, 2021). "In summary, we have found that ACTN1 is closely related to grade II/III gliomas prognosis, and its expression is positively correlated with T cell exhaustion-related gene expression, indicating that ACTN1 may affect T cell exhaustion within tumors." (PMID 38307919, 2024). "We further found that ACTN1 is closely related to grade II/III gliomas prognosis, and its expression is positively correlated with T cell exhaustion-related gene expression, indicating that ACTN1 may affect T cell exhaustion within tumors." (PMID 38307919, 2024). "Given that we have discovered a close association between the four-gene signature and immunity and that ACTN1 expression is negatively correlated with the prognosis of grade II/III glioma patients, we hypothesize that ACTN1 may affect T-cell exhaustion within tumors." (PMID 38307919, 2024). "We validated the clinical relevance of ACTN1 protein expression using immunohistochemistry and found that ACTN1 expression is negatively correlated with grade II/III gliomas patient prognosis." (PMID 38307919, 2024). "In this study, we constructed a novel and highly robust four-gene signature (ACTN1, AQP1, LAMC3, and NRM) based on EMT-related genes to predict grade II/III gliomas prognosis." (PMID 38307919, 2024). "In conclusion, ACTN1 is highly expressed in various tumors, and its expression is negatively correlated with grade II/III gliomas patient prognosis." (PMID 38307919, 2024). "Cellular experiments showed ACTN1, AQP1 and NRM promoted glioma cell proliferation, migration and invasion." (PMID 38307919, 2024). "Based on this, we believe that ACTN1 could be used as a target for regulating immune checkpoints, such as PD-1, TIM3, and LAG-3, to treat grade II/III gliomas." (PMID 38307919, 2024). "Immunohistochemistry further validates the clinical relevance of ACTN1 protein expression, suggesting that ACTN1 may serve as an important prognostic marker in grade II/III gliomas." (PMID 38307919, 2024). "Targeting the ACTN1, AQP1 and NRM genes may offer new therapeutic opportunities to improve grade II/III gliomas patient outcomes." (PMID 38307919, 2024). "Our previous data have demonstrated a negative correlation between ACTN1 mRNA expression and grade II/III gliomas prognosis." (PMID 38307919, 2024).
endometriosis (3 papers, 2021 to 2025). The growth of functional endometrial tissue in anatomic sites outside the uterine body. "The authors confirmed that ACTN1 protein and ACTN1 mRNA levels were elevated in all endometriosis samples compared to controls, especially in umbilical endometriosis, where the increase reached 273% and 266% for protein and mRNA levels, respectively." (PMID 40072086, 2025). "Currently, there are no reports on the impact of ACTN1 expression on the migratory potential of endometriosis cells, but some evidence suggests its role in the development of endometriosis." (PMID 40072086, 2025). "Nevertheless, an increase in ACTN1 does not lead to malignancy of the process in endometriosis, which would be expected for forms of extragenital endometriosis due to high ACTN1 content." (PMID 34440202, 2021).
gastric cancer (3 papers, 2021 to 2024). A primary or metastatic malignant neoplasm involving the stomach. "We constructed loss and gain of function gastric cancer cells, which revealed the effect of ACTN1 over-expression on promoting GC cell proliferation, invasion, migration, and inhibited apoptosis." (PMID 34546849, 2021). "Then the EDU incorporation, the assay revealing the proliferation ability of cells, showed that knocking down ACTN1 significantly reduced the proliferation ability of gastric cancer cells, while the overexpression enhanced the proliferation ability." (PMID 34546849, 2021). "High-throughput sequencing and public microarray datasets from the Gene Expression Omnibus (GEO) and The Cancer Genome Atlas (TCGA) revealed the upregulation of ACTN1 in gastric cancer with a poor prognosis." (PMID 34546849, 2021). "In our study, we for the first time demonstrated that ACTN1, acting as an oncogene, prompts tumorigenesis and EMT of gastric cancer, and subsequently explored the underlying mechanism." (PMID 34546849, 2021). "Integrin subunit alpha 5 (ITGA5) and integrin subunit beta 5 (ITGB5) may form a heterodimer in gastric cancer that positively interacts with ACTN1 to promote proliferation, invasion, and EMT." (PMID 39228892, 2024). "Altogether, these results demonstrated that ACTN1 could be a promising candidate for gastric cancer treatment." (PMID 34546849, 2021). "The role of ACTN1 in gastric cancer still needs to be further developed." (PMID 34546849, 2021). "The role of ACTN1 in the occurrence and development of gastric cancer was first identified." (PMID 34546849, 2021). "Mechanistic studies revealed that ACTN1 regulates the epithelial-mesenchymal transition (EMT) and tumorigenesis of gastric cancer via the AKT/GSK3β/β-catenin pathway." (PMID 34546849, 2021). "Mechanistic studies revealed that ACTN1 regulates the epithelial-mesenchymal transition (EMT) and tumorigenesis of gastric cancer via the AKT/GSK3β/β-catenin pathway, confirmed by the inhibitor of AKT MK2206." (PMID 34546849, 2021). "After a detail investigation of the mechanism, we found that ACTN1 upregulation enhanced the phosphorylation of GSK3β and AKT, as well as, Snail expression levels in gastric cancer." (PMID 34546849, 2021). "We explored the function of ACTN1 in gastric cancer (GC), which has largely remained unclear." (PMID 34546849, 2021). "By identifying the lysine group of succinylation in gastric cancer tissues, it was found that ZER, ACTN1 and other down-regulated succinylated proteins were related to the activity of cytoskeletal, and may be closely associated with the metastasis of gastric cancer." (PMID 37777749, 2023). "However, the role of ACTN1 has not yet been reported in gastric cancer." (PMID 34546849, 2021).
glioblastoma (3 papers, 2009 to 2018). The most malignant astrocytic tumor (WHO grade IV). "Our functional enrichment of genes in patient tumors revealed that low expression of RND1 in glioblastoma induces an overexpression of focal adhesion proteins like extracellular matrix proteins (COL1A1 and LAMB1); integrins (ITGA5 and ITGB1); actin-binding proteins (FLNA; ACTN1) and vinculin." (PMID 30333910, 2018).
ovarian carcinoma (3 papers, 2018 to 2025). A malignant neoplasm originating from the surface ovarian epithelium. "Collectively, we uncovered that LLGL2 impaired actin filament aggregation into bundles by interacting with ACTN1, which led to cytoskeleton remodeling and inhibition of the invasion and metastasis of ovarian cancer cells." (PMID 38136424, 2023). "We found that LLGL2 altered the intracellular localization and function of ACTN1 by interacting with ACTN1 and regulating cytoskeleton remodeling to inhibit the invasion and metastasis of ovarian cancer cells." (PMID 38136424, 2023). "Overall, our results suggested that LLGL2 interacted with ACTN1 and affected the affinity of ACTN1 and actin, thereby leading to cytoskeletal remodeling of ovarian cancer cells and to the inhibition of their invasion and metastasis." (PMID 38136424, 2023). "We uncovered that LLGL2 altered the intracellular localization and function of ACTN1 by interacting with ACTN1 and regulated cytoskeleton remodeling to inhibit the invasion and metastasis of ovarian cancer." (PMID 38136424, 2023). "Mechanistically, LLGL2 altered the intracellular localization and function of ACTN1 by interacting with ACTN1 and regulating cytoskeleton remodeling to inhibit the invasion and metastasis of ovarian cancer cells." (PMID 38136424, 2023). "Expression changes and possible functional impact of ACTN1, MPST, ERP29 and SERPINB6 are reported for several cancers, but not for ovarian cancer." (PMID 29344361, 2018).
platelet disorder (3 papers, 2014 to 2017). "Several platelet disorders have been associated with mutations in genes involved in actin organization, including Wiskott-Aldrich syndrome protein (WASP) and Actinin alpha 1 (ACTN1)." (PMID 24859754, 2014).
bleeding disorder (2 papers, 2018 to 2025). "Another one of our top candidates, ACTN1, is also involved in actin regulation and, even more interestingly, has also been linked to blood and bleeding disorders." (PMID 30453955, 2018).
Bowen disease (2 papers, 2022 to 2024). "Genetic variants and differential expression of the ACTN1 have been reported in various diseases, including congenital macrothrombocytopenia, Angelman syndrome, Bowen disease, postmenopausal osteoporosis, lupus erythematosus, and COVID-19." (PMID 37935791, 2024). "And next, among 20 proteins, 8 proteins (TNC, FSCN1, SERPINB1, ACTN1, RAB31, COL3A1, COL1A1 and CD36) expressed levels showed significant differences between CSCC and Bowen disease." (PMID 36085041, 2022). "Our proteomics results showed expression of FSCN1 and ACTN1 were significant higher in CSCC relative to Bowen disease, and FSCN1 as well as ACTN1 may related to the proliferation, invasion and migration in CSCC progression process." (PMID 36085041, 2022). "Besides, the proteins of TNC, FSCN1, SERPINB1, ACTN1 and RAB31 in CSCC were significantly up-regulated, while COL3A1, COL1A1 and CD36 were significantly down-regulated relative to Bowen disease in proteomics results." (PMID 36085041, 2022).
cardiac hypertrophy (2 papers, 2016 to 2023). "Data also showed up-regulation of about 180 genes including Tgfb2, Ace, Atf3, Ctgf, Angpt14, Col9a2, Wisp2, Nppa, Nppb, and Actn1 that are linked to cardiac muscle contraction, cardiac hypertrophy, cardiac fibrosis and myocardial injury." (PMID 27548259, 2016).
heart failure (2 papers, 2020). Inability of the heart to pump blood at an adequate rate to meet tissue metabolic requirements. "The expression of most of the pro-fibrotic and EndoMT mediating genes like CTGF, SNAI1, SNAI2, Twist 1 and 2, BMP4, and Actn1 are upregulated during heart failure and most of these are down-regulated at Week 19 (recovery)." (PMID 33584806, 2020).
malignant glioma (2 papers, 2021). A grade III or grade IV glioma arising from the central nervous system. "ACTN1, a gene related to the microenvironment, shows prognostic value in patients with malignant glioma." (PMID 34367317, 2021).
nemaline myopathy (2 papers, 2025). Nemaline myopathy (NM) encompasses a large spectrum of myopathies characterized by hypotonia, weakness and depressed or absent deep tendon reflexes, with pathologic evidence of nemaline bodies (rods) on muscle biopsy. "Intriguingly, nuclear abnormalities similar to those here described have been reported in other CM with variants in sarcomeric genes, having been analysed in detail in a transgenic model of nemaline myopathy with an ACTN1 variant." (PMID 40488356, 2025).
schizophrenia (2 papers, 2020 to 2025). A major psychotic disorder characterized by abnormalities in the perception or expression of reality. "TRAF6, PRKACA and ACTN1 are all connected to both SRC and PSEN1 and therefore it might be useful to further investigate their interactions in order to better understand the mechanisms that could be involved in Schizophrenia." (PMID 32735660, 2020).
Stroke (2 papers, 2015 to 2019). Sudden impairment of blood flow to a part of the brain due to occlusion or rupture of an artery to the brain. "Of these, APLP1, NPTXR, ACTN1 also were detected in the brain tissue of CI/R-induced stroke mice." (PMID 30645580, 2019). "In this proteomics study, the neurogenesis-related proteins, Actn1, Gap43, Gfap, and neurofascin (Nfasc) were upregulated after the CIR-induced stroke (Neurogenesis sector)." (PMID 26492191, 2015).
amyotrophic lateral sclerosis (1 paper, 2020). Amyotrophic lateral sclerosis (ALS) is a neurodegenerative disease characterized by progressive muscular paralysis reflecting degeneration of motor neurons in the primary motor cortex, corticospinal tracts, brainstem and spinal cord. "Expression changes of ACTN1 were associated with AD in hippocampus, whereas NFIL3 was associated with neuroprotection in models of Amyotrophic Lateral Sclerosis." (PMID 32493431, 2020).
asthma (1 paper, 2022). "Interestingly, five of these loci, i.e., ACTN1, PDS5B, SEMA6D, SPRY4, and TENM3, have been reported of association with the genetic susceptibility of asthma." (PMID 36051697, 2022).
autosomal dominant macrothrombocytopenia (1 paper, 2013). This syndrome is characterized by congenital thrombocytopenia associated with the presence of large platelets. "In summary, using positional cloning and targeted NGS, we identified a causative mutation in the ACTN1 gene in a large French family with autosomal dominant macrothrombocytopenia." (PMID 24069336, 2013).
Cirrhosis (1 paper, 2022). A chronic disorder of the liver in which liver tissue becomes scarred and is partially replaced by regenerative nodules and fibrotic tissue resulting in loss of liver function. "We also observed that genes associated with cytoskeleton and focal adhesion, such as ACTN1 and CTTN, are up-regulated and are related to HCV-mediated cirrhosis." (PMID 36016316, 2022).
epidermoid carcinoma (1 paper, 2025). "Next, we evaluated the in vitro activity and off-target mitigation potential of ACTN1 siRNAs modified with iBu and MOP at positions 6-7 (line 6) in the A431 epidermoid carcinoma cell line." (PMID 40737088, 2025).
glomerular disease (1 paper, 2020). "Actn1-knockout mice are not viable while Actn4-deficient mice develop a severe glomerular disease indicating that Actn1 does not compensate for the loss of α-actinin-1." (PMID 32774516, 2020).
head and neck squamous cell carcinoma (1 paper, 2023). A squamous cell carcinoma that arises from any of the following anatomic sites: lip and oral cavity, nasal cavity, paranasal sinuses, pharynx, larynx, and salivary glands. "The aim of this study was to detect the expression levels of α-Actinin 1 (ACTN1) and ITGA5 in HNSCC and to explore how ACTN1/ITGA5 regulated the proliferative and invasive abilities, as well as the EMT of Head and neck squamous cell carcinoma (HNSCC) cells." (PMID 36742137, 2023).
hereditary thrombocytopenia (1 paper, 2022). "ACTN1 was found to be correlated with hereditary thrombocytopenia." (PMID 36292752, 2022).
infarction (1 paper, 2024). A localised pathological necrosis of tissue resulting from obstruction of the blood supply usually by a thrombus, an embolus, or vascular torsion. "In contrast, the downregulation of proteins such as ACTN1, MYL9, CSRP1, COMP, and PI16, which are closely associated with muscle cell development and contractility, suggests a disruption in muscular and structural integrity within the heart in the acute phase post-infarction." (PMID 39513871, 2024).
ischemic stroke (1 paper, 2025). A stroke disorder caused by obstruction of blood flow to the brain, due to thrombotic (local blood clot formation) or embolic (due to a blood clot or other material traveling from another site) event. "Furthermore, we observed an increase in ACTN1, a protein recently identified alongside coagulation factor F5 as a novel biomarker linked to coagulation and the immune microenvironment in ischemic stroke." (PMID 41463387, 2025).
liver cancer (1 paper, 2021). An epithelial or non-epithelial malignant neoplasm that arises from the liver. "The result showed that ACTN1 was commonly up-regulated in liver cancer cells compared to LO2 cells." (PMID 33413564, 2021). "Firstly, we detected the mRNA expression of ACTN1 in 9 liver cancer cell lines and the non-malignant LO2 cells." (PMID 33413564, 2021).
lung disease (1 paper, 2023). "In our study, this pathway was significantly extracted from general SSc (upregulated proteins) and lung disease related to SSc (downregulated proteins) subgroups (ITGB1;ACTN1;ICAM1;ITGAM;MMP9)." (PMID 36732374, 2023).
oral cancers (1 paper, 2018). "LMNA has been implicated in the modulation of TGF-β1 on collagen production and mesenchymal differentiation, and ACTN1 up-regulation has been described in stromal fibroblasts derived from oral cancers." (PMID 29593339, 2018).
osteoporosis (1 paper, 2022). A condition of reduced bone mass, with decreased cortical thickness and a decrease in the number and size of the trabeculae of cancellous bone (but normal chemical composition), resulting in increased fracture incidence. "There was a study found that ACTN1 was a potential risk of osteoporosis, and the main biological function of ACTN1 was to regulate the binding of actin cytoskeleton and calcium ions, so as to affect the ability of osteogenesis." (PMID 36204467, 2022).
pancreatic cancer (1 paper, 2022). "Decreased expression of ACTN1 may improve survival in pancreatic cancer." (PMID 36131343, 2022).
uterine corpus endometrial carcinoma (1 paper, 2016). A endometrial carcinoma (disease) that involves the body of uterus. "For example, ACTN1 (33rd by MUFFINN yet below 8000th by the gene-centric methods in uterine corpus endometrial carcinoma (UCEC) samples) is known to have a tumor-specific splice variant in many types of cancer." (PMID 27333808, 2016).